TMPRSS2 (transmembrane serine protease 2)
Diseases named in the same sentence as TMPRSS2 in open-access papers (continued):
Sharing a sentence is not in itself a finding about the gene and the disease.
COVID-19 (continued). "As ACE2 and TMPRSS2 are involved in SARS-CoV-2 virus entry in the human host, with the present findings, we hypothesize the inclusion of the present extract in protection devices, such as surgical masks, functioning as physical barriers against COVID-19." (PMID 34361576, 2021). "Accordingly, the reduction of the TMPRSS2 expression by blocking the androgen receptor would decrease SARS-CoV-2 entry into human cells, which is corroborated by studies showing protection from more severe states related to COVID-19 with the use of antiandrogens." (PMID 33643746, 2021). "In this context, a key factor to understand this apparent paradox in the pathophysiology of COVID-19, related to the conflicting evidences ACE2’s role, could be found in the delicate interplay balance between the cleavage of ACE2 by both ADAM17 and TMPRSS2 proteases in a stepwise fashion." (PMID 33117379, 2020). "The results showed that compared with normal subjects, the expression levels of AAK1 and TMPRSS2 in patients who had been infected with SARS-CoV-2 were significantly down-regulated, suggesting that COVID-19 patients may consume lots of AAK1 and TMPRSS2 in the advanced stage of the disease." (PMID 33195212, 2020). "Thus, the interactions of TMPRSS2 with SARS-CoV-2, together with its structural variability, gene–gene interactions, expression regulation profiles, and pharmacogenomic properties, characterize this gene as a potential target for COVID-19 therapy." (PMID 33375616, 2020). "The nonoverlapping expression of ACE2 and TMPRSS2 and weaker expression of TMPRSS2 compared with ACE2 are consistent with recent single-cell RNA-Seq data reporting lack of coordinated cotranscription of ACE2 and TMPRSS2 in placentas predating the COVID-19 pandemic." (PMID 33351086, 2020). "Increased expression of ACE2 and TMPRSS2 may not be the only way these proteins enhance the severity of COVID-19-related lung disease." (PMID 33372179, 2020). "Of these, the estrogen-related compounds (estradiol and genistein) and the androgen receptor antagonist (enzalutamide) block TMPRSS2, which is required for SARS-CoV-2 spike protein priming and appear to be the most promising repurposing candidates for symptom amelioration in COVID-19 patients." (PMID 32764454, 2020). "According to the authors, this absence of TMPRSS2 and Furin expression by olfactory receptor neurons could determine an early recovery of anosmia in patients with COVID-19." (PMID 32612515, 2020). "Despite the common feature in Enceph patients with and without COVID-19 regarding the imbalance between TMPRSS2 zymogen and the active fragment, the reason why CoV-Enceph patients do not present an overall increase in protein levels, as in Enceph patients, is unknown." (PMID 40036349, 2025). "Additionally, in severe COVID-19 patients, it has been observed a differential methylation in the promoters of the Angiotensin Converting Enzyme 2 (ACE2) receptor gene, which the SARS-CoV-2 virus exploits to enter host cells, and of the Transmembrane Serine Protease 2 (TMPRSS2), that processes it." (PMID 39497009, 2025). "Additionally, although the assessment of TMPRSS2 expression could have offered additional insights into forecasting the outcome of COVID-19, there were no remaining blood samples available to conduct these specific tests." (PMID 39188881, 2024). "Since the transmembrane serine protease 2 (TMPRSS2) and angiotensin-converting enzyme 2 (ACE2) proteins are involved in SARS-CoV-2 viral entry, we investigated whether TMPRSS2 was elevated in the urine of COVID-19-positive participants compared to the urine of COVID-19-negative participants." (PMID 39861814, 2024). "Furthermore, of particular relevance to COVID-19, one notes that P. aeruginosa may facilitate SARS-CoV-2 entry into airway epithelial cells by amplifying local abundance of the COVID-19-promoting host protease TMPRSS2." (PMID 37987478, 2023).
COVID-19 (continued). "The increased ACE-2 and decreased TMPRSS2 expressions might explain the lower impact of SARS-CoV-2 in patients with CF; however, our study contrasts with the present literature because our patients with CF and COVID-19 presented worse outcomes than those infected by other viruses." (PMID 37444770, 2023). "Valproic acid can reduce the expression of angiotensin-converting enzyme 2 and transmembrane serine protease 2 required for SARS-CoV-2 virus entry, and reduces pathological atrial remodeling thereby preventing the development of AF, which may be a candidate for COVID-19 and AF therapy." (PMID 36352845, 2022). "In addition, previous studies have pointed out that the androgen receptor (AR) signal controls the expression of TMPRSS2, and TMPRSS2 is necessary for the SARS-CoV-2 spike protein to infect the human body, so androgen receptor inhibitors are used and have therapeutic potential for COVID-19." (PMID 35057070, 2022). "The mechanism of TCM treatment for COVID-19 may be to prevent SARS-CoV-2 from entering cellular host by reducing viral replication and transcription, interfering with viral binding to ACE-2 receptors, and decreasing the expression of type 2 transmembrane serine protease (TMPRSS2)." (PMID 36684919, 2022). "Furthermore, whilst ACE2 and TMPRSS2 are potentially important in determining infection and therefore the dermatological clinical signs and symptoms of COVID-19, our work, together with that of others, does not seem to confirm this hypothesis." (PMID 36139051, 2022). "Thus, sex differences in ACE-2 and TMPRSS-2 protein expression observed in mice may not explain the higher disease burden of COVID-19 among men." (PMID 34907257, 2021). "This evidence indicates that for successful SARS-CoV-2 infection, cellular ACE2 and TMPRSS2 are necessary, and male sex hormones may contribute to the infectibility of the host (a recent clinical study reported that among 191 COVID-19 inpatients, 62% were male; among non-survivors 70% were male)." (PMID 32354022, 2020). "The colocalization of ACE2 and TMPRSS2 in zona fasciculata and zona reticularis of adrenal cortex suggests that SARS-CoV-2 may directly interfere with the process of cortisol synthesis, thereby further increasing the incidence of CIRCI in COVID-19 critical ill patients." (PMID 33488517, 2020). "This evidence postulates that ACE2 and concomitant TMPRSS2 expression in pericytes and cardiomyocytes could essentially potentiate chances of SARS-CoV-2 infection in the systemic CV system and also explain the higher prevalence of CV issues in COVID-19 patients." (PMID 32645974, 2020). "These cells, C2BBe1 intestinal cells with a brush border having high levels of transmembrane serine protease 2 (TMPRSS2), showed robust viral propagation, and could be persistently infected with SARS-CoV-2, supporting the clinical observations of persistent GI infection in COVID-19 patients." (PMID 32969768, 2020). "Indeed, the pro-thrombotic state notably present during COVID-19, as well as hematological, kidney, hepatic, cardiovascular, neurological and gastrointestinal manifestations extensively reported in COVID-19, are largely mediated by abnormalities in the RAAS, ACE2, and TMPRSS2." (PMID 32993622, 2020). "Notably, differential ACE2 cleavage mediated by ADAM17/TMPRSS2 may have a significant impact on the pathophysiology of COVID-19, since TMPRSS2-mediated ACE2 cleavage does not enhance ACE2 shedding from the cell surface, inhibiting the shedding process mediated by ADAM17." (PMID 40431631, 2025). "In patients with severe COVID-19 admitted to hospital, urine ACE2 increase 2–300 times with no sex difference, while TMPRSS2 is more abundant in uEVs from male patients." (PMID 39382598, 2025). "TMPRSS2 was not, or barely, detected in the ACE2-precipitated eluate of COVID-19 patients, suggesting no co-localization with ACE2 in uEVs." (PMID 39382598, 2025).
COVID-19 (continued). "We detected a significant upregulation of NRP1 transcripts in vascular ECs in COVID-19 lungs compared with noninfectious controls (P < 7.5E-6), while ACE2 and TMPRSS2 expression remained unchanged." (PMID 41159753, 2025). "For TMPRSS2, IL-17A, ADAM-17, and AP, values were significantly higher in all non-healthy groups (previously infected, mild, and severe COVID-19) compared to healthy individuals." (PMID 40003732, 2025). "Distribution of ACE-1 (rs4343), TMPRSS2 (rs12329760) and ACE-2 (rs908004) SNPs Genotypes among severe and non-severe COVID-19 patients." (PMID 37426824, 2023). "The distribution of ACE-1 (rs4343), TMPRSS2 (rs12329760) and ACE-2 (rs908004) SNP genotypes among severe, non-severe COVID-19 patients and healthy control was analyzed." (PMID 37426824, 2023). "However, since both compounds decrease ACE2 and TMPRSS2 expression and ultimately prevent SARS-CoV-2 infectivity in vitro (albeit with different IC50 values), further research is needed to define the precise mechanisms that could account for disparate clinical outcomes in COVID-19 treatment." (PMID 37459541, 2023). "Why and how do immune responses and inflammation in the blood of COVID-19 patients be induced without ACE2 and TMPRSS2?" (PMID 37087411, 2023). "There are currently no reports on the functional roles of ACE2/ADAM17/TMPRSS2 and CD146 in sex differences of disease, neither on CDK nor on COVID-19." (PMID 35887687, 2022). "Nonstructural proteins, spike glycoproteins, TMPRSS2, and ACE2 are important drug targets for anti-COVID-19 treatment." (PMID 36291025, 2022). "A study that offered a mechanistic correlation to severe disease showed that the expression levels of placental ACE2 (but not TMPRSS2 or Furin) and the protein levels of IFITM1 and IFITM3 were higher in women with severe COVID-19." (PMID 35492217, 2022). "Although the suggested compounds do not inhibit another essential host serine protease, TMPRSS2, a combination therapy with TMPRSS2 inhibitors, such as nafamostat, camostat, and gabexate mesylate, could improve the treatment efficacy in patients who have COVID-19." (PMID 35745663, 2022). "Anosmia is thought to occur in COVID-19 via binding of the virus to the host receptors of the ACE2 and TMPRSS2 proteases that express themselves in the nonneural olfactory epithelium." (PMID 34777862, 2021). "In the COVID-19 patients who did not require a ventilator, ACE2 was expressed in CD14 monocytes, CD4 memory and naive T cells, and dendritic cells; TMPRSS2 was expressed in several immune cells." (PMID 34578338, 2021). "In order to study the role of diabetes on cardiomyocyte alterations, independently of COVID-19, we investigated ACE2, glycosylated ACE2, and TMPRSS2 proteins in cardiomyocytes from DM and Non-DM explanted-hearts." (PMID 33962629, 2021). "In HNECs treated with HMGB1 and OSM, upregulation of the COVID-19-related genes TMPRSS6, furin, and cathepsin L (CTSL) was observed compared to the control, while no change of ACE2 or TMPRSS2 was observed." (PMID 34445093, 2021). "In this setting, in the immunoblotting analysis of explanted hearts from non-COVID-19 patients, we found an increase of glycosylated ACE2 and TMPRSS2 protein content in DM vs. Non-DM specimens." (PMID 33962629, 2021). "Therefore, over-activation of ADAM17 and TMPRSS2 could be the main mechanism underlying the negative effects of RAS imbalance, acute inflammation and intravascular coagulation observed in elderly males with COVID-19 comorbidities." (PMID 33117379, 2020). "The levels of TMPRSS2, osteopontin, furin, and ACE2 in fixed lung tissue samples from COVID-19 patients with and without diabetes can be assessed." (PMID 33238570, 2020). "However, to the best of our knowledge, the role of ACE2, TMPRSS2, and TLR-7, in the different outcomes of COVID-19, between men and women, has not been fully demonstrated." (PMID 38088954, 2023).
COVID-19 (continued). "However, when two of the protease inhibitors, Camostat and Nafamostat, employed to demonstrate an important role of TMPRSS2 in SARS-CoV-2 infection in cell culture, were employed for COVID-19 treatment in humans, moderate or no efficacy was observed." (PMID 36851486, 2023). "scRNAseq of bronchoalveolar lavage fluid from intubated COVID-19 patients detected SARS-CoV-2 sequences in monocyte-derived alveolar macrophages and migratory dendritic cells, although neither ACE2 nor TMPRSS2 could be detected in either cell type." (PMID 36453030, 2023). "However, to the best of our knowledge, it has not yet demonstrated the role of ACE2, TMPRSS2, and TLR7 in the different outcomes of COVID-19 between men and women." (PMID 36768959, 2023). "At the beginning of the COVID-19 pandemic, it was believed that the SARS-CoV-2 utilizes the plasma membrane fusion as the default pathway but can switch to the endosomal pathway in the absence of the plasma membrane protease TMPRSS2." (PMID 36438831, 2022). "Finally, despite preclinical data, it is also possible that androgens do not regulate TMPRSS2 and ACE2 in relevant tissues to an extent that is targetable by antiandrogen therapy to ameliorate severity of COVID-19 in patients." (PMID 35438754, 2022). "Conversely, TMPRSS2 overexpression may justify the higher occurrence of COVID-19 complications in males, particularly in those with androgenetic alopecia (AGA), in which TMPRSS2 is likely more activated compared to non-AGA males." (PMID 32993622, 2020). "Notably, the neurological symptoms reported in COVID-19 patients should be seriously considered, but the mechanism remains obscure since no cell type expressing both ACE2 and TMPRSS2 has been found in the CNS." (PMID 32942748, 2020). "In case of COVID-19 patients, autologous and allogenic MSC transplantation could be applied, because MSCs do not express ACE2 and TMPRSS2; therefore, patient’s own MSCs cannot be infected by SARS-CoV2." (PMID 33059757, 2020). "In addition, despite hypoxic upregulation of ACE2 and TMPRSS2 in HLMVECs, we did not observe any enhancing effect of hypoxia on SARS-CoV-2 infection, the condition that could prime lung EC activation state in COVID-19." (PMID 37071849, 2023). "To functionally validate our observations of autopsy tissue of COVID-19 patients we performed infection experiments with two adrenal cortical cell lines (HAC15 which was positive for ACE2 and TMPRSS2 and SW13 which showed weak ACE2 expression and was negative for TMPRSS2)." (PMID 35332140, 2022). "In absence of TMPRSS2, the virus and ACE2 undergo endocytosis, which together with protease-mediated shedding of ACE2 down-regulates the cell surface levels of ACE2 and may ease the COVID-19 disease." (PMID 36367091, 2022). "Interestingly, in the pooled COVID-19 patients, dendritic cells expressed ACE2 but not TMPRSS2." (PMID 34578338, 2021). "This gender discrepancy of COVID-19–related morbidity and mortality can be attributed to a combination of biological sex differences, including differences in sex hormones involved in inflammatory processes and in expression levels of ACE2 and TMPRSS2, but literature data are not yet coherent." (PMID 34595175, 2021). "Although the exact roles of ACE2 and TMPRSS2 as mediators of SARS-CoV-2 infection has not been well determined, the observed upregulation of both in air pollution, and pulmonary fibrosis may explain the spread and aggravation of COVID-19 by these two conditions." (PMID 33706759, 2021). "Thus, in cell types where AR regulation of ACE2 and TMPRSS2 does not exist, the broader transcriptional repression by BET inhibitors may block expression of these key host factors, and agents targeting BET proteins may have a different therapeutic efficacy in COVID-19 than direct AR inhibitors." (PMID 33310900, 2020).
prostate carcinoma (696 papers, 2006 to 2026). A carcinoma that arises from epithelial cells of the prostate gland. "Selection against TMPRSS2, a serine protease implicated in viral entry and prostate cancer with 43% sequence identity to matriptase, yielded binders with micromolar inhibitory potency." (PMID 41959119, 2026). "The TMPRSS2 gene in prostate cancer, e.g. has a risk variant in its promoter associated with oncogenic translocation of the promoter onto ERG." (PMID 40198231, 2025). "A higher level of MTAP staining was linked to TMPRSS2:ERG fusion positive prostate cancers (p < 0.0001)." (PMID 40554389, 2025). "PTEN mutations, which are present in 20–40% of prostate cancers, occur more commonly in patients with TMPRSS2-ERG fusions." (PMID 40075623, 2025). "Elevated TMPRSS2 levels have been observed in high-risk prostate cancer (Grade 3-4) compared to low-risk cases (Grade 1-2)." (PMID 41244516, 2025). "Transcriptional activation of pericentromeric heterochromatin driven by EWS::FLI1 in Ewing sarcoma and TMPRSS2 fusion proteins in prostate cancer yield pathogenic RNAs, which transmit genotoxic stress." (PMID 38530366, 2024). "FT has additionally been associated with higher risk of ERG‐positive prostate cancers, which have an androgen‐induced fusion between the androgen‐regulated TMPRSS2 gene and the oncogene ERG." (PMID 38234143, 2024). "Prostate cancer organoids retain parental genetic features, including TMPRSS2–ERG fusion, SPOP mutation, SPINK1 overexpression, and CHD1 loss." (PMID 39309690, 2024). "The TMPRSS2-ERG mutation plays a vital role in the transition from pre-malignant states to prostate cancer." (PMID 38791108, 2024). "The identification of the TMPRSS2:ERG fusion as a frequent molecular alteration occurring in nearly half of prostate cancer cases has revolutionized our comprehension of the underlying mechanisms driving this malignancy." (PMID 37511059, 2023). "There were also 5 KLF5K369Q-downregulated and NTZ-upregulated genes whose lower expression levels in human prostate cancers were also significantly associated with worse overall survival, including TMPRSS2, CALB1, SPOCK2, COL4A4, and COL4A3." (PMID 36810084, 2023). "Other studies have reported a lower frequency of PTEN loss and TMPRSS2-ERG translocations in genetic analyses of primary prostate cancers from Black men, strengthening the reliability of these findings." (PMID 37721753, 2023). "The TMPRSS2:ERG fusion is considered relevant to prostate cancer, but its association with the development and progression as well as its clinical significance have not been fully elucidated." (PMID 37511059, 2023). "TMPRSS2 is associated with the development of prostate cancer and the promotion of SARS‐CoV‐2 infection of lung cells." (PMID 36975376, 2023). "The expression of the TMPRSS2 gene has been associated with cases of prostate cancer (PC) and COVID-19." (PMID 37878968, 2023). "The exact molecular mechanisms underlying the pathogenic role of TMPRSS2: ERG fusion in prostate cancer are yet to be fully uncovered, but there is evidence suggesting its association with the clinical course of the disease." (PMID 37185705, 2023). "The presence of the TMPRSS2::ERG fusion in prostate cancer is associated in part with cancer recurrence, and commonly corresponds to a more aggressive malignancy and overall poorer clinical prognosis." (PMID 37509339, 2023). "Men with higher androgen receptor transcriptional activity have a higher risk of TMPRSS2-ERG fusion-positive prostate cancer." (PMID 35017320, 2022). "In humans, TMPRSS2 overexpression and gene rearrangements have been identified as an underlying mechanism in prostate cancer development and progression." (PMID 36309092, 2022). "Since TMPRSS2 is an androgen-dependent gene, the fusion protein encoded by TMPRSS2/ERG is overexpressed in prostate cancer, which contributes to tumor progression." (PMID 35954308, 2022).